BCL2 (BCL2 apoptosis regulator)
Diseases named in the same sentence as BCL2 in open-access papers (continued):
Sharing a sentence is not in itself a finding about the gene and the disease.
lymphoma (continued). "While it is difficult to compare BCL-2 levels between our lymphomas and the lymphomas from the Eμ-Myc/Eμ-Bcl-2 double transgenic mice (note human BCL-2 was used in this model), we found similar expression levels by Western blotting." (PMID 35961968, 2022). "ABT199/venetoclax inhibition of BCL-2 has been reported to result in compensatory upregulation of the anti-apoptotic MCL1 in lymphoma and neuroblastoma cell lines." (PMID 35154579, 2022). "There were a number of genes related to apoptosis including Bcl2 (B-cell CLL/lymphoma), Cflar (CASP8 and FADD-like apoptosis regulator), and Nkg7 (natural killer cell group 7 sequence)." (PMID 36552094, 2022). "Delivered to cells gynomically (i.e., without conjugates or transfectants), it was efficiently internalized by a range of cell lines (melanoma, lymphoma and fibrosarcoma) and was more potent than Oblimersen at reducing Bcl-2 expression." (PMID 35056993, 2022). "For example, Z-DNA sequences have been found to be located near translocation breakpoints in the c-MYC and BCL-2 genes, implicating them in the development of lymphomas and leukemias." (PMID 40766048, 2022). "The elevated BCL-2 expression observed in the CRISPRa transduced lymphoma cells substituted for MCL-1 and hence increased resistance to the MCL-1 selective inhibitor S63845." (PMID 35961968, 2022). "In other settings, such as lymphoma and pulmonary fibrosis, downregulation of Bcl-2 expression by inhibition of JAK signaling was demonstrated." (PMID 36355485, 2022). "Feline lymphomas—particularly those arising from T lymphocytes—were more likely to show high Bcl-2 expression via immunohistochemistry in several studies." (PMID 35448666, 2022). "So far, therapies for lymphomas and other cancers have focused on inhibition of cellular regulatory proteins (i.e., the mitoprotective members of the Bcl-2 family such as Bcl-2, Bcl-xL, and Mcl-1)." (PMID 35806271, 2022). "The anti-apoptotic nature and up-regulated level of BCL2 in the majority of DHL-BCL2 lymphoma and other malignancies have raised interest in developing inhibitors targeting BCL2 and its family members." (PMID 35303910, 2022). "Studies have shown that CDX binding sites are required to mediate Oct-2 ability to activate bcl-2 in lymphomas impacting cell survival." (PMID 33412518, 2021). "Here, we present the first MYC/BCL2/BCL6 triple-hit lymphoma patient receiving murine and human CAR T cell therapy and expect to provide insights into the therapeutic strategy for such patients." (PMID 34078654, 2021). "COO classification and diphenotypic lymphoma (high expression of Bcl2 and c-Myc protein) are commonly known prognostic indicators for clinicians." (PMID 34956871, 2021). "Twenty-eight percent of the patients with DLBCL presented BCL6 rearrangement, 25% presented c-MYC rearrangement, and 16% presented BCL2 rearrangement, with 16% presenting double-hit lymphomas." (PMID 34819573, 2021). "Consistent with this, oncogenic mutations in Ezh2, combined with Bcl2 overexpression, also gave rise to early onset DLBCL lymphomas in Cγ1Cre;VavP:Bcl2;Ezh2Y641F/N and in irradiated wild-type mice transplanted with Ezh2Y641F-transduced VavP:Bcl2-derived HPCs." (PMID 34207773, 2021). "For example, several of our top genes showed a tight SNV clustering pattern associated with elevated expression, including MYC, BCL2, PIM1 and IGLL5 in lymphoma." (PMID 33554123, 2021). "In total, PLIER identified 137 rearrangements involving MYC, BCL2, and BCL6: 56 MYC rearrangements (in 49 lymphoma samples), 39 BCL2 rearrangements (in 34 samples), and 42 BCL6 rearrangements (in 40 samples)." (PMID 34099699, 2021). "In fact, BCL2 overexpression has been shown to delay tumour onset in animal models of irradiation-driven lymphoma and myelodysplastic syndrome transition into AML." (PMID 34903710, 2021).
lymphoma (continued). "The anti-tumor activities of Bcl-2 integrating CAR-T cells (20BBZ-Bcl-2) were evaluated in vitro and in a mouse xenograft lymphoma model." (PMID 33429845, 2021). "DLBCL, NOS “double expressor” seems to correlate with a worst prognosis, but the double expression of these two proteins is not necessarily a surrogate indicator of double translocation of c-MYC and BCL2 genes (“double-hit lymphomas”)." (PMID 34030716, 2021). "The aberrant expression of the Bcl-2 protein contributes to the pathogenesis of many types of human malignancies, including leukemias and lymphomas." (PMID 33412518, 2021). "In our current probe panel for lymphoma, we targeted the BCL2, BCL6, and MYC genes, bus also included the immunoglobulin loci IGH, IGK, IGL, and other loci implicated in hematolymphoid malignancies." (PMID 34099699, 2021). "Bcl-2 is an anti-apoptotic gene, which is overexpressed in a variety of tumors, including leukemia and lymphoma." (PMID 34512363, 2021). "Exposure of the lymphoma cells to nanomolar doses of KPT-9274 led to a significant reduction in the expression of Bcl-2 (pro-survival marker) and enhanced expression of pro-apoptotic markers, such as cleaved-Caspase-3 and cleaved-PARP." (PMID 35008323, 2021). "The second patient was a 60-year-old man with hepatic involvement and 60% to 70% MYC expression and 50% to 70% BCL-2 expression by IHC, consistent with a double-expressing lymphoma." (PMID 33311588, 2021). "In line with this, translocations in lymphomas and leukemias occur either in oncogenes active at some stages of B cell maturation (like BCL2, MYC) or in genes orchestrating B cell development and activation (e.g., CD79B, PAX5)." (PMID 34210001, 2021). "The bcl‐2 oncogene, an inhibitor of apoptosis, is overexpressed in many lymphomas as well as in melanomas." (PMID 33219744, 2021). "The two effects together (direct and indirect) reprogram mRNA translation in a way that promotes lymphoma cell death and sensitises to BCL2 inhibition." (PMID 33318657, 2021). "Among them, BCL-2 inhibitors are the most widely used senolytics, although originally developed as therapies for lymphoma." (PMID 34873338, 2021). "In contrast, 28% of the patients with DLBCL presented BCL6 rearrangement, 25% presented c-MYC rearrangement, and 16% presented BCL2 rearrangement, with 16% presenting double-hit lymphomas." (PMID 34819573, 2021). "Here, we examine the effect of a synthetic eIF4A inhibitor (CR-1-31 B) against aggressive, MYC and BCL2 positive lymphomas and we specifically explore potential mechanisms of resistance to the eIF4A inhibitor treatment." (PMID 33562682, 2021). "BCL2 positivity in lymphoma cells was 25%–50% in nine patients (53%), 51%–75% in one patient (5.8%), and >75% in seven patients (41.2%)." (PMID 34938664, 2021). "EVs derived from lymphoma cells were shown to express c-Myc, Bcl-2, Mcl-1, CD19, and CD20 and stimulate angiogenesis by delivering angiogenic proteins, including VEGF." (PMID 33805807, 2021). "Within B-NHL, Bcl-2 overexpression commonly arises from genetic abnormalities and is substantially different in several lymphoma subtypes." (PMID 33412518, 2021). "The MALT-lymphomas showed enlarged meshworks of CD23(+) follicular dendritic cells colonized by CD20(+) Bcl2(+), Bcl6(−) and CD10(−) B lymphocytes." (PMID 33467055, 2021). "MYC protein expression has been shown to be a poor prognostic factor in the rituximab era, which is compounded by BCL2 co-expression (double-positive or double-expressor lymphomas)." (PMID 34404436, 2021). "It was previously suggested that in addition to promoting SASP, p65 reinforces cell cycle arrest in senescent Eμ‐myc lymphomas expressing the anti‐apoptotic protein Bcl‐2." (PMID 33459422, 2021).
lymphoma (continued). "Diffuse large B-cell lymphoma (DLBCL) with co-expression of MYC and BCL2 proteins is referred to as double expressor lymphoma." (PMID 34282799, 2021). "Another important consideration is the presence of genetic rearrangements of the MYC, BCL2, and BCL6 genes that identifies patients with what is called double- or triple-hit lymphomas (MYC with BCL2 and/or BCL6 rearrangements)." (PMID 34945817, 2021). "Overexpressed MYC and BCL2 in double-hit lymphoma and double expressing lymphoma has poor prognosis." (PMID 34372899, 2021). "BCL2-positivity was found in 56% of patients, whereas double-expressor lymphomas represented 17% of cases." (PMID 34945856, 2021). "Recent studies have identified that certain subpopulations of DLBCL and BL contain MYC, Bcl-2 and/or Bcl-6 translocations and were called “double hit” lymphoma (DHL) or “triple hit lymphoma” (THL)." (PMID 33412518, 2021). "We and others have shown the feasibility of eIF4A inhibitors against a range of cancers including leukemia, non-Hodgkin’s lymphoma—especially MYC+/BCL2+ lymphomas, and perhaps more modestly against pancreatic cancer." (PMID 33562682, 2021). "In this study, we investigated the preclinical anti-lymphoma efficacies and potential mechanism of action of a novel treatment approach, combining the BCL2 inhibitor venetoclax with CS2164, a new orally active multitarget inhibitor, in HGBL-DHL models." (PMID 33777762, 2021). "The nearly universal involvement of these genes in FL established aberrant epigenetic regulation as a central driving force in this lymphoma type, in addition to BCL2 deregulation." (PMID 34456919, 2021). "There was also significant enrichment in disease gene sets (from DisGeNET33) related to leukaemia and lymphoma (P < 0.01), including proto-oncogenes such as BCL2 and MYC." (PMID 33637755, 2021). "Preclinical models also showed that combining BETi with the BH3 mimetic, BCL-2 antagonist venetoclax was beneficial in MYC-overexpressing lymphoma cells." (PMID 35008680, 2021). "We find that this type of therapy is highly effective against aggressive and MYC+/BCL2+ lymphoma cells in vitro and in vivo." (PMID 33562682, 2021). "This study also demonstrated that silvestrol synergized with the BCL2 inhibitor ABT-199 to kill lymphoma cell lines in vitro." (PMID 32924027, 2020). "FBXO10 binds to the anti-apoptotic oncoprotein BCL-2 and promotes its degradation, thereby initiating cell death in lymphomas." (PMID 32545767, 2020). "Together, these preclinical studies show that although circulating lymphoma cells appear to be primarily dependent on BCL-2, conferring high sensitivity to venetoclax, extrinsic signals can modulate this dependence." (PMID 32183335, 2020). "MYC/BCL2 double‐hit lymphomas tend to demonstrate themselves with advanced stage and poor prognostic parameters including extranodal infiltration and elevated LDH,10, 27 and a high FLIPI score." (PMID 32459397, 2020). "Our results show mutations at loop anchors are associated with upregulation of the cancer driver genes BCL2 and MYC in malignant lymphoma thus pointing to a possible new mechanism for their dysregulation via alteration of insulator loops." (PMID 32216817, 2020). "Low-grade lymphomas containing a BCL2 rearrangement need subsequent secondary genetic hits for the disease to evolve." (PMID 32102485, 2020). "Rare cases of follicular lymphoma transform to a high-grade B-cell lymphoma with MYC and BCL2 rearrangements or "double-hit lymphoma"." (PMID 32183313, 2020). "The study clearly showed a decrease in Bcl-xL and Bcl-2 protein expression in canine lymphoma cell lines under the action of both tested compounds, however, it was demonstrated that (+)-(4R, 5S, 6R)-1 isomer was characterized by higher activity." (PMID 32260403, 2020).
lymphoma (continued). "Hippuristanol plus ABT-737 (an inhibitor of Bcl-2) synergistically increased cell death in Myc-driven lymphomas; likewise, the inhibition of eIF4AI is enough to improve the chemosensitivity of Myc-driven lymphomas to ABT-737." (PMID 33066449, 2020). "DLBCL with overexpression of Myc and Bcl-2 represents a unique category of high-grade lymphoma with inferior overall survival." (PMID 32334477, 2020). "Another significant outcome was that the Co-expression of c-MYC and BCL2 induced lymphoma was spontaneous and occured at an early age." (PMID 32695674, 2020). "Venetoclax (ABT-199), a highly selective BH3 mimetic, is designed to treat lymphomas with BCL-2 translocations." (PMID 32296035, 2020). "The effects of our top-ranked molecules were first tested on A375, a melanoma cell line expressing high levels of XIAP, and a Jurkat T-lymphoma cell line expressing high levels of Bcl-2." (PMID 32587235, 2020). "The first member of the BCL-2 family to be identified was the pro-survival B-cell lymphoma-2 (Bcl-2) gene, which was found to be frequently amplified in lymphomas by an oncogenic translocation." (PMID 32335811, 2020). "Whereas systemic DLBCL with co-expression of c-Myc and Bcl-2 (double-expressor) and/or co-rearrangement of MYC and BCL2 and/or BCL6 (double or triple hit lymphoma) has been associated with a worse prognosis, the findings were inconclusive for PCNS DLBCL." (PMID 33322508, 2020). "MCL-1 has been identified as a resistance factor for venetoclax in multiple studies, indicating that survival of lymphoma cells can be mediated by both BCL-2 and MCL-1." (PMID 33308268, 2020). "In agreement, another preclinical study demonstrated that the combination of statins with venetoclax was cytotoxic to DLBCL, CLL, and AML cells and reduced lymphoma burden in a syngeneic mouse model of BCL-2/MYC driven “double hit” lymphoma." (PMID 32183335, 2020). "DH/TH lymphomas are predominantly derived from germinal center B (GCB) cell COO subtypes typically resulting from BCL2 translocations." (PMID 33168821, 2020). "In order to test the effect of varying the levels of miR-5008 on BCL2 expression, we transfected the lymphoma cell lines FL18 and U2932 with either a mimic of miR-5008 or a scrambled control sequence." (PMID 33233721, 2020). "Venetoclax (VCX) is a selective BCL-2 inhibitor approved for the treatment of leukemia and lymphoma." (PMID 33414642, 2020). "C-MYC expression > 40% and BCL2 expression in > 50% of lymphoma cells were detected altogether in 12/58 (21%) cases." (PMID 32613279, 2020). "Taken together, we show that targeting c-MYC and BCL2 expression into mouse GC B cells or pan-B cells generates a clinically relevant mouse model of double-expressor lymphoma." (PMID 32695674, 2020). "The BCL-2 gene is the first cell death regulator identified by its frequent translocation in a well-studied subtype of lymphoma in humans, the follicular B-cell lymphoma (FL)." (PMID 32549409, 2020). "Later on, it was discovered that the aberrant expression of BCL-2 protein contributes to the pathogenesis of many types of human malignancies, including leukemias, lymphomas, and cancers." (PMID 32290241, 2020). "DLBCL associated with translocation of MYC and BCL2 and/or BCL6 (double-hit or triple-hit lymphomas) needs to be investigated in the context of high risk for CNS relapse of primary breast DLBCL." (PMID 32781541, 2020). "In FL and DLBCL, the translocation and activation of c-MYC and B-cell lymphoma 2 (BCl2) is regarded as “double-hit lymphoma” because of the poor survival of patients with this pattern of genetic alteration." (PMID 33168041, 2020). "Those who received HPCs with knocked-down Kmt2d expression in addition to increased Bcl2 expression exhibited early onset of lymphoma, splenomegaly, and histopathological evidence of high-grade FL." (PMID 33277464, 2020).
lymphoma (continued). "Given the fact that anti-apoptotic BCL-2 proteins play a crucial role in lymphoma pathogenesis, disease progression and drug resistance, the efforts to target them therapeutically have been underway for several decades." (PMID 32290241, 2020). "Many features of canine diffuse large B-cell lymphoma resemble the ABC form of human DLBCL, including constitutive activation of the NF-kB pathway, and almost universal presence of double expressing MYC/BCL2 lymphomas." (PMID 32038991, 2020). "Double expressor DLBCL is the concomitant expression of Myc and Bcl-2 proteins during lymphomas which results in poor prognosis of patients." (PMID 32334477, 2020). "Certain malignancies, mostly leukemias and lymphomas, appear addicted to a single pro-survival protein (mainly BCL-2)." (PMID 32337074, 2020). "Experimental studies demonstrated that deletion or down-regulation of miR-15a leads to overexpression of B cell lymphoma 2 (BCL2), which is a common phenomenon of Lymphoma." (PMID 32260218, 2020). "Downregulation of Bcl-xl expression induced lymphoma cell apoptosis in follicular lymphoma cells with high expression of Bcl-2 and Bcl-xl." (PMID 31892356, 2019). "Consistent with the enforced expression of BCL2 and MYC, we saw strong enrichment for signatures of double hit lymphoma, a subtype of lymphoma characterized by translocation of both MYC and BCL2 and associated with a particularly poor clinical outcome." (PMID 31586074, 2019). "22.4% of patients (11/49) were positive for both c-MYC and BCL-2 proteins, and was considered as double-expression lymphoma (DEL)." (PMID 31702637, 2019). "In lymphoma, BCL2 translocations bypass this effect by driving BCL2 expression through alternative immunoglobulin enhancers and promoters." (PMID 30874354, 2019). "Correlation between the lymphoma type, EZH2 mutation status, MYC, BCL2 and BCL6 rearrangements and DZNep sensitivity." (PMID 31419226, 2019). "We find that BM-1197 exerts potent growth-inhibitory activity against lymphoma cells that harbor high expression of Bcl-2 and Bcl-xL in vitro and has a synergistic effect with chemotherapeutic drugs." (PMID 31892356, 2019). "Another study from the same group has shown that NLRP3 inflammasome activation promoted lymphoma cells proliferation and inhibited apoptosis through up-regulation of c-myc and bcl-2 anti-apoptotic factors." (PMID 31379813, 2019). "High levels of this B-cell growth factor are known to increase BCL-2 expression in lymphoma cells, and to correlate with a worse prognosis in DLBCL patients." (PMID 31293984, 2019). "The combination of BET inhibitors and BCL2 inhibitors decreased drug resistance in MYC-related lymphomas." (PMID 31403034, 2019). "We aimed to address the impact of the lymphoma type, EZH2 mutation status, as well as MYC, BCL2 and BCL6 translocations on the sensitivity of the lymphoma cell lines to DZNep-mediated apoptosis." (PMID 31419226, 2019). "We have previously shown that this tendency towards creation of novel Ets binding motifs is found in other gene promoters, like BCL2 in lymphoma or NEAT1 in liver cancer." (PMID 31109337, 2019). "Exemplarily, our analysis provided a close look on the transition range between FL and DLBCL, on DLBCL with poor prognosis showing expression patterns resembling that of BL, and particularly on ‘double-hit’ MYC and BCL2 transformed lymphomas." (PMID 31039827, 2019). "The percentages of Bcl-2 expression in individual lymphoma types vary somewhat in different reports." (PMID 31146399, 2019). "Five patients carried all the three rearrangements, so called “triple hit lymphoma” (THL – MYC+/BCL2+/BCL6+) and for survival analysis were considered among DHLs." (PMID 31976479, 2019). "BCL2, the eponym of the BCL2 family, was initially observed in the late 1970s through its upregulation due to chromosome 14 translocations in lymphomas." (PMID 31013740, 2019).